ELL2 (elongation factor for RNA polymerase II 2)
Description:
Elongation factor component of the super elongation complex (SEC), a complex required to increase the catalytic rate of RNA polymerase II transcription by suppressing transient pausing by the polymerase at multiple sites along the DNA. Component of the little elongation complex (LEC), a complex required to regulate small nuclear RNA (snRNA) gene transcription by RNA polymerase II and III. Plays a role in immunoglobulin secretion in plasma cells: directs efficient alternative mRNA processing, influencing both proximal poly(A) site choice and exon skipping, as well as immunoglobulin heavy chain (IgH) alternative processing. Probably acts by regulating histone modifications accompanying transition from membrane-specific to secretory IgH mRNA expression.
Synonyms: MRCCAT1
Tractability: PROTAC: UniProt records ubiquitination sites on it; ubiquitination databases record sites on it.
Gene: Protein-coding gene on chromosome 5 (95,885,098 to 95,961,871, reverse strand). Ensembl gene ENSG00000118985.
Subcellular location: Nucleus
Subcellular location (Human Protein Atlas): Nucleoplasm
Pathways (Reactome):
Gene expression (Transcription): RNA polymerase II transcribes snRNA genes
Gene Ontology:
Molecular function: protein binding; cis-regulatory region sequence-specific DNA binding
Biological process: snRNA transcription by RNA polymerase II; positive regulation of snRNA transcription by RNA polymerase II; positive regulation of transcription elongation by RNA polymerase II; transcription elongation by RNA polymerase II
Cellular component: nucleoplasm; transcription elongation factor complex; nucleus
Genetic constraint (gnomAD): Loss-of-function variants: 15 observed, 66.3 expected, observed/expected ratio (o/e) 0.23, 90% interval 0.15 to 0.35. The upper end of that interval is the gene's LOEUF score, 0.35, which puts it in group 1 of 6, group 1 being the genes least tolerant of losing a copy. Missense variants: 544 observed, 749.47 expected, observed/expected ratio (o/e) 0.73, 90% interval 0.68 to 0.78. Synonymous variants: 257 observed, 277.96 expected, observed/expected ratio (o/e) 0.92, 90% interval 0.83 to 1.02.
Homologues: Orthologues: chimpanzee ELL2 (99% identical), macaque ELL2 (99% identical), pig ELL2 (95% identical), dog ELL2 (94% identical), guinea pig ELL2 (93% identical), rabbit ELL2 (91% identical), mouse Ell2 (90% identical), rat Ell2 (85% identical), tropical clawed frog ell2 (69% identical), zebrafish ell2 (52% identical), Drosophila melanogaster Su(Tpl) (22% identical), Caenorhabditis elegans ell-1 (14% identical). Paralogues in human: ELL (47% identical), ELL3 (20% identical), MARVELD2 (15% identical), OCLN (14% identical), OCEL1 (8% identical).
Diseases named in the same sentence as ELL2 in open-access papers:
ELL2 is named in the same sentence as 31 diseases in open-access papers, as found by Europe PMC text mining. Sharing a sentence is not in itself a finding about the gene and the disease. The quoted sentences say what the papers report.
multiple myeloma (9 papers, 2015 to 2024). "Associations for increased serum IgA levels and lower multiple myeloma risk have been reported at rs3815768-T and rs56219066-C, respectively, in LD (R2 > 0.8) with our lead SNP rs11744881-T at ELL2, here associated with lower IgA N-glycan sialylation." (PMID 39123268, 2024). "A genome-wide association study conducted in multiple myeloma discovered that ELL2 mutation is associated with total IgA levels." (PMID 31275443, 2019). "The multiple myeloma risk allele confers lower ELL2 expression, which is associated with reduced levels of IgA and IgG." (PMID 31275443, 2019). "Downregulated expression of transcription regulators in high-risk UM could help identify potential tumor-suppressor genes, however only the downregulation of ELL2 is associated with prostate cancer and multiple myeloma based on our current knowledge." (PMID 35954332, 2022). "The ELL2 gene has been implicated in cancers such as multiple myeloma and salivary gland carcinoma." (PMID 31930204, 2019). "Missense mutation in ELL2 gene affects IgA and IgG level associated with multiple myeloma." (PMID 30972099, 2019). "ELL2 was recently discovered as a susceptibility gene for multiple myeloma (MM)." (PMID 29695719, 2018). "Recently, we identified ELL2 as a susceptibility gene for multiple myeloma (MM)." (PMID 29695719, 2018). "Intriguingly, while ELL2 associates also with IgG sialylation, the multiple myeloma risk allele rs56219066-C shows a stronger association with circulating IgA levels compared to IgG, suggesting that IgA, more than IgG, N-glycan sialylation may play a role in multiple myeloma." (PMID 39123268, 2024). "For example, an apaQTL in the ELL2 gene (rs56219066) is correlated with increased usage of an intronic PAS and is associated with risk for multiple myeloma." (PMID 32584258, 2020). "Previous evidences showed that ELL2 was deregulated expressed in prostate cancer and myeloma." (PMID 31275443, 2019). "IgA N-glycans associations at the ST6GAL1, MGAT3, and ELL2 loci were also identified in QMDiab, with lead SNPs at the ST6GAL1 and ELL2 loci being coincident or in strong linkage disequilibrium (LD) with previously reported associations for IgA nephropathy and multiple myeloma risk, respectively." (PMID 39123268, 2024).
prostate carcinoma (6 papers, 2016 to 2024). A carcinoma that arises from epithelial cells of the prostate gland. "ELL2 has been reported to contribute to prostate homeostasis and potentially acts as a tumor suppressor in the development and progression of prostate cancer cells." (PMID 38741036, 2024). "ELL2 downregulation is seen in prostate cancer specimens and other observations indicate that its decrease improves cell proliferation, migration, and invasion." (PMID 32316460, 2020). "ELL2 has been identified as an androgen response gene in immortalized normal human prostate epithelial cells as well as prostate cancer cell lines LNCaP and C4-2." (PMID 32316460, 2020). "Interestingly, the expression of its binding partner ELL2 is also induced by androgens in prostate cancer cells, suggesting that EAF2 and ELL2 expression are induced coordinately by androgens in the prostate." (PMID 27058417, 2016).
Stroke (2 papers, 2020 to 2024). Sudden impairment of blood flow to a part of the brain due to occlusion or rupture of an artery to the brain. "Other identified genes previously reported in GWAS to be associated with CVD-related traits were ELL2 (GWAS of BP, insulin and glucose), TRPS1 (GWAS of BP), PID1 (GWAS of stroke, lung function and chronic obstructive pulmonary disease) and WIPF1 (GWAS of resting heart rate)." (PMID 31999706, 2020).
Anxiety (1 paper, 2019). Intense feelings of nervousness, tension, or panic often arise in response to interpersonal stresses. "Closest genes to this isolated SNP include a pro-protein convertase gene PCSK1 and an elongation factor gene ELL2, neither of which have been linked to anxiety in any species." (PMID 30655508, 2019).
breast carcinoma (1 paper, 2012). "ELL2 is a Breast Cancer Antioestrogen Resistance (BCAR) 1 gene which control anti-oestrogen-resistant cell growth resistance (BCAR)." (PMID 23216862, 2012).
cataract (1 paper, 2023). Partial or complete opacity of the crystalline lens of one or both eyes that decreases visual acuity and eventually results in blindness. "Importantly, the present analyses identify as yet unappreciated and novel high-priority candidates in the lens for defining new pathways involved in lens biology (e.g., Ell2 and Prdm16) that likely also contribute to the cataracts resulting from Celf1 deficiency." (PMID 37048143, 2023).
colon cancer (1 paper, 2022). "We also found that TF ELL2, not reported in existing studies, was associated with colon cancer." (PMID 35186035, 2022).
Crohn disease (1 paper, 2023). A gastrointestinal disorder characterized by chronic inflammation involving all layers of the intestinal wall, noncaseating granulomas affecting the intestinal wall and regional lymph nodes, and transmural fibrosis. "ROC analysis demonstrated excellent predictive ability of DAPP1 and ELL2 for intestinal inflammation in Crohn’s disease, with AUCs exceeding 0.8." (PMID 38059894, 2023). "Similarly, DAPP1 and ELL2 were upregulated in Inflamed Crohn’s disease samples." (PMID 38059894, 2023).
fetal growth restriction (1 paper, 2024). A fetus that does not grow beyond the 10th percentile of conventionally accepted weight for gestational age. "Placental mRNA expression was examined for the 8 genes enriched in isolated trophoblast side-population cells (CXLC8/IL8, ELL2, GATA6, HK2, HLA-DPB1, INTS6, SERPINE3, UPP1) in placentas obtained from participants with early onset preeclampsia (n = 78) or fetal growth restriction (n = 30)." (PMID 39028417, 2024).
glioblastoma multiforme (1 paper, 2020). "By the targeting of ELL2 by microRNA-299 in glioblastoma multiforme, the upregulation of microRNA-299 is associated with a poor prognosis." (PMID 32063749, 2020).
HIV-1 infection (1 paper, 2024). The type species of lentivirus and the etiologic agent of acquired immunodeficiency syndrome (AIDS). "However, knock-out of the other SEC components either did not alter HIV-1 infection (AFF4, ELL2, AF9) or resulted in a very slight, but statistically significant increase in infection (AFF1, ENL)." (PMID 39259751, 2024).
knee osteoarthritis (1 paper, 2024). "Specifically, cinnamaldehyde may affect knee osteoarthritis by regulating apoptosis-related genes such as ZFAND5, BCL6, ELL2, FOSL2, MARCKS, and SGCD." (PMID 39376659, 2024).
osteoarthritis (1 paper, 2024). A noninflammatory degenerative joint disease occurring chiefly in older persons, characterized by degeneration of the articular cartilage, hypertrophy of bone at the margins and changes in the synovial membrane. "Firstly, the identified APDEGs—MARCKS, ZFAND5, BCL6, FOSL2, ELL2, and SGCD—may provide deeper insights into osteoarthritis pathogenesis." (PMID 39376659, 2024).
preeclampsia (1 paper, 2024). Preeclampsia is a hypertensive disorder of pregnancy that is characterized by new-onset hypertension with proteinuria presenting after 20 weeks of gestation, and depending on mild or severe forms may initially present with severe headache, visual disturbances, and hyperreflexia. "Moreover, ELL2 was downregulated in first trimester placentas obtained from chorionic villous sampling preceding a preeclampsia diagnosis." (PMID 39028417, 2024).
Sepsis (1 paper, 2023). Sepsis is defined as life-threatening organ dysfunction caused by a dysregulated host response to infection. "The genes TPSO, CYP1B1, LCN2, CLIC2, and ELL2 were up-regulated and FTO was down-regulated in sepsis compared to the uncomplicated infections (p < 0.05)." (PMID 36820206, 2023). "Interestingly, two transcriptional factors were identified as up-regulated genes in sepsis from our analysis: NFE2 and ELL2." (PMID 36820206, 2023).
tumor (8 papers, 2011 to 2024). "In this review, we summarize what is known about ELL2 with respect to its role in driving B cell to plasma cell differentiation as well as its potential role in tumor suppression." (PMID 31930204, 2019). "In particular, this included genes involved in secretory pathways, lipid and sugar metabolism (such as, UGDH, SORD, GLUD1, ELOVL5, ASCL3, UAP1), but also genes implicated in tumor progression and metastasis with functions in cell survival, proliferation and adhesion (EHF, ELL2, TPD52, MAFB, SGK)." (PMID 21829708, 2011). "Accepting this caveat, our findings are consistent with differential expression of ELL2 being important in the early phase of MM tumor development rather than disease progression per se." (PMID 28903037, 2017).
ELL2 also shares sentences with these, for which no sentence is quoted: clear cell renal cell carcinoma (6 papers); cancer (3); IgA Nephropathy (2); bacterial meningitis (1); chronic obstructive pulmonary disease (1); endometrial adenocarcinomas (1); endometrial cancer (1); infection (1); leishmaniasis (1); lung (1); metastatic tumors (1); placental insufficiency (1); plasmacytoma (1); salivary gland carcinoma (1); uveal melanoma (1).